ABCB5 (ATP binding cassette subfamily B member 5)
Diseases named in the same sentence as ABCB5 in open-access papers (continued):
Sharing a sentence is not in itself a finding about the gene and the disease.
cancer (continued). "In summary, most of the literature on ABCB5 has focused on its role as a marker of cancer stem cells and its implication in cancer biology and MDR." (PMID 39267923, 2024). "ABCB5 plays a key role in multidrug resistance in cancer cells, exporting chemotherapy drugs and reducing their effectiveness." (PMID 39238930, 2024). "Accumulating evidence revealed that the inhibition of ABCB5 had an impact on the malignant potential of cancer cells both in vitro and in vivo." (PMID 36790659, 2023). "ABCB5 has been reported to be overexpressed in HCC and as being associated with chemoresistance, cancer stemness properties, and poor recurrence-free survival." (PMID 36557005, 2022). "In the present study, using Stitch EMBL, the interaction network analysis revealed that a coordination of candidate proteins (FKBP4, ESRRA, IGSF10 and ABCB5) was involved in KEGG pathways of many cancers." (PMID 36517562, 2022). "It has been reported that ABC transporter genes such as ABCG2 and ABCB5 often become upregulated in cancers of pancreas, breast, lung, ovary, and skin, and can be the potential targets for therapy." (PMID 34358102, 2021). "Suppression of LINC00963 effectively reduced the cancer aggressiveness and sensitized chemotherapy through the downregulation of ABCB5." (PMID 32357409, 2020). "Our results demonstrated that the LINC00963-mediated cancer stemness and resistance to chemotherapy were through ABCB5." (PMID 32357409, 2020). "In particular, ABCB5 belongs to sub‐family B of the ABC transporter superfamily, and has been reported to be overexpressed in HCC, associated with chemoresistance, cancer stemness properties and poor recurrence‐free survival." (PMID 32783366, 2020). "Most importantly, we showed that the repressed self-renewal, invasion, and colony-forming capacities after a silence of LINC00963 were all reversed by overexpression of ABCB5, suggesting that LINC00963-mediated cancer stemness was through regulation of ABCB5." (PMID 32357409, 2020). "Since ABCB5 functionally controlled cancer stemness properties and chemoresistance, the expression levels were analysed with genotypes." (PMID 32783366, 2020). "Through the use of a monoclonal antibody against ABCB5, the authors were able to induce cancer cell sensitivity to drugs such as doxorubicin." (PMID 32823711, 2020). "We have chosen three ABC-transporters, i.e., P-glycoprotein (MDR1/ABCB1) and breast cancer resistance protein (BCRP/ABCG2) as well-known MDR-mechanisms and ABCB5 as novel efflux transporter relevant for cancer stem-like cells." (PMID 29707146, 2018). "Overexpressed ABCB5 (ATP-binding cassette transporter, subfamily B, member 5) has been shown to efflux anti-cancer drugs from cancer cells." (PMID 29929490, 2018). "Another potential CIC target is ABCB5, a novel human multidrug resistance mediator recently shown to be expressed by cells of melanocytic lineage and additional cancers responsible for resistance to chemotherapy in vitro." (PMID 34221246, 2017). "Our data demonstrate a molecular signature expression for ABCB5 and Lgr5 as gene profile for cancer cells with specific characteristics for chemo resistance and self-renewal in the bone marrow of patients with CRC." (PMID 34221246, 2017). "A limited number of previously published studies on MDR and the expression of ABC transporters other than ABCB5 have reported the presence of significant effects on cancer cell metabolism." (PMID 27560924, 2016). "Further studies will reveal if this approach can be extended to additional cancer cell lines expressing ABCB5, or to alternative, related ABC transporters." (PMID 27560924, 2016). "ABCB5 expression has also been discovered in the subpopulation of several cancer cells containing the cancer stem cell (CSC)." (PMID 26843453, 2016).
cancer (continued). "ABCB5 is a member of the ABC protein superfamily, which includes the transporters ABCB1, ABCC1 and ABCG2 responsible for causing drug resistance in cancer patients and also several other transporters that have been linked to human disease." (PMID 21298007, 2011). "Together, these studies suggested that ABCB5 may be involved in inducing the cancer stemness and the formation of TME, further study is required to study the regulatory mechanism." (PMID 40746888, 2025). "Additionally, ABCB5 is considered a cancer cell marker, mediating chemoresistance through drug transport." (PMID 39941329, 2025). "Notably, significant correlation was observed between ABCA10 expression and clinical outcome in 10 cancer types, and between ABCB5 expression and prognosis in 6 cancer types." (PMID 40445912, 2025). "Previous research indicated that ABCB5 was involved in inducing the cancer stemness of OSCC." (PMID 40746888, 2025). "Taken together, they represent a promising tool for cancer research and targeting of ABCB5." (PMID 39267923, 2024). "Interestingly, most of the literature investigating the role of ABCB5 as a marker of CSC has focused on this cancer type." (PMID 39267923, 2024). "Studies have investigated the potential role of ABCB5 in cancer multidrug resistance." (PMID 37958830, 2023). "Hence, elevated expression of MDR1 and ABCB5 confirms a multidrug-resistant phenotype in almost all cancer cells." (PMID 37509203, 2023). "In addition, ABCB5 is involved in processes that lead to the resistance of cancer cells to anti-neoplastic agents." (PMID 35008260, 2021). "Additional cancer types were evaluated for the prognostic significance of ABCB5 expression levels." (PMID 32783366, 2020). "Therefore, we treated cancer cell lines expressing different MDR conferring genes (P-glycoprotein, BCRP, ABCB5 and mutation-activated EGFR) with BetA." (PMID 29867487, 2018). "Interestingly, another betulin derivative, betulinic acid (BA), was also determined as not being a substrate of any of the three ABC transporters (MDR1/ABCB1, ABCG2 and ABCB5), but the cancer cells overexpressing these transporters were efficiently responded to by BA." (PMID 36979107, 2023). "Published HCC genomics cohorts (TCGA, AMC and Inserm) showed corroborating data that ABCB5 mutation rate and copy number variation in HCC was rare event (2.6%, 22/851), where the ABCB5 expression data were similarly compared to different patient cohorts and cancer types." (PMID 32783366, 2020). "MSC500 suppressed the stemness genes as well as CSC markers (Oct4, Sox2, ABCB5, Gli1, Notch1, and β-catenin) in the side population of GBM8401 cancer cells." (PMID 34358102, 2021). "Analysis of TCGA (the Cancer Genome Atlas) datasets suggested that the level of LINC00963 was positively correlated with the expression of the cancer stemness markers (Sox2 and CD44) and drug resistance markers (ABCG2 and ABCB5)." (PMID 32357409, 2020). "ABCB5 represents a novel resistance-mediating ABC-transporter, which is expressed in cancer stem-like cells." (PMID 27092478, 2016). "The molecular importance of ABCB5 in promoting cancer stemness and chemoresistance is underscored by their findings, which suggest that targeting LINC00963 could sensitize resistant cancer cells and improve therapeutic outcomes in OSCC patients." (PMID 40445912, 2025). "While T cells displayed a negative correlation with ABCB5 expression in several cancer types, exceptions were observed in BRCA, PCPG, PAAD, and UVM." (PMID 40445912, 2025). "All of the taxol-resistant cancer cells demonstrated overexpression of ABCB5 when compared with the taxol-sensitive counterparts suggested that the taxol-resistant MCF-7, HCT-8 and A549 are multidrug resistance, in part, due to ABCB5 overexpression." (PMID 28903398, 2017).
cancer (continued). "Considering the compelling evidence regarding IL-1β-mediated regulation of HIF-1α, a key regulator of PFKP and the glycolysis pathway in cancer cells, we further dissected if the IL-1β-HIF-1α signaling cascade is involved in ABCB5-mediated regulation of glycolysis." (PMID 27560924, 2016). "Following a comprehensive literature review, ATP binding cassette subfamily A member 10 (ABCA10) and ATP binding cassette subfamily B member 5 (ABCB5) were selected as key candidates for downstream analysis due to the absence of systematic pan-cancer analysis of these genes." (PMID 40445912, 2025). "All of these data support the fact that ABCB5 may not directly potentiate chemoresistance, but may be responsible for increasing heterogeneity in the cancer cell population." (PMID 29929490, 2018). "Taken as a whole, ABCB5 may not directly potentiate doxorubicin resistance, but responsible for increasing heterogeneity in the cancer cell population." (PMID 20649952, 2010). "Other pathways that were consistently modulated by ABCB5+ MSC grafting regardless of the administration route were those involved in signal transduction, in the immune and endocrine system, in cancers, and in infectious diseases." (PMID 38274791, 2023).
ABCB5 also shares sentences with these, for which no sentence is quoted: epithelial ovarian cancers (2 papers); head and neck carcinoma (2); acute leukemia (1); anemia (1); bladder cancer (1); breast tumors (1); cardiomyopathy (1); Cerebral ischemia (1); colon adenocarcinoma (1); degenerative diseases (1); genetic disorders (1); hematological malignances (1); hypersensitivity (1); infectious disease (1); ischemic stroke (1); junctional epidermolysis bullosa (1); kidney diseases (1); kidney injury (1); laryngeal carcinoma (1); leukaemias (1); liver disease (1); lymph node metastasis (1); lymphoma (1); malignant pleural mesothelioma (1); medulloblastoma (1); metastatic disease (1); neuroblastoma (1); nevus (1); ovarian cancer (1); prostate adenocarcinoma (1).
A further 7 diseases each share a sentence with ABCB5 in 1 paper.